IL6R (interleukin 6 receptor)
Diseases named in the same sentence as IL6R in open-access papers (continued):
Sharing a sentence is not in itself a finding about the gene and the disease.
cancer (continued). "Tocilizumab, an antibody that competitively inhibits the binding of IL-6 to its receptor (IL-6R), is already used by oncologists to reduce pulmonary distress in cancer patients during immune checkpoint inhibitors." (PMID 36362770, 2022). "IL-6R and pSTAT-3 are upregulated in advanced cancer and are detected at higher levels in samples of bone, lymph node and visceral metastasis compared with normal tissue." (PMID 35703345, 2022). "The inhibitor related to the blockage of IL-6 and IL-6R such as tocilizumab is considered as an effective anti-cancer therapeutic approach." (PMID 36091805, 2022). "In IL6Rα-overexpressing cancer cells, SSTP1 induces apoptosis at low concentration through JNK pathway, without causing significant membrane disruption." (PMID 34867962, 2021). "Our results further our previous observations that IL-6 augments Cisplatin-induced cancer cell stemness, implicating Cisplatin and IL-6R signaling as mediators of phenotypic changes in HNSCC tumors that result in enhanced stemness." (PMID 34689150, 2021). "The SSTP1-induced growth inhibition of cancer cells was significantly inhibited by anti-IL6Rα and SC144, whereas LMT28 was ineffective." (PMID 34867962, 2021). "The anti-IL6R antibody tocilizumab is already used to treat inflammation-related disorders and is currently in clinical trials to treat different cancer types." (PMID 34834425, 2021). "Its functions included inhibition of IL-6R/STAT3 signaling by binding to IL-6R mRNA in cancer cells as well as inhibition of the IL-6 molecule in TAMs by CPEB3." (PMID 34944712, 2021). "Overexpression of circCHIPK3 inhibits the expression of miR-124 and increases the expression of miR-124 target gene, interleukin 6 receptor (IL6R), which leads to cancer cell proliferation." (PMID 33718387, 2021). "We show that SSTP1, a novel HDP identified by shotgun cloning, binds to the active IL6/IL6Rα/gp130 complex on cancer cells, rearranging the active site residues." (PMID 34867962, 2021). "Our results on IL6R methylation deserve further validations studies to fill this current gap in the literature concerning cancer, IL6 signaling, and its epigenetic regulation." (PMID 34576335, 2021). "The soluble (s)IL-6R-dependent trans-signaling mediated by ADAM17 was verified as one of the reasons for the development of many cancers including lung cancer, ovarian cancer, pancreatic cancer, colorectal cancer and hepatocellular cancer." (PMID 34182543, 2021). "In MDA-MB-231 cells, SSTP1-induced cell death primarily depending on the activation of JNK, implying the SSTP1-induced JNK activation is sufficient to induce cell death in IL6Rα-overexpressing cancer cells." (PMID 34867962, 2021). "As an important effector in several signaling pathways, IL6R was also proposed as a new therapeutic target for some cancers." (PMID 33789615, 2021). "Inflammatory processes and cancer progression are highly connected, mediated by cytokines like the IL-6R and other immunomodulatory molecules in the tumor microenvironment." (PMID 34692768, 2021). "All these studies suggested that ADAM17-mediated cleavage of the IL-6R is responsible for the tumorigeneses and progression of cancer." (PMID 34182543, 2021). "Computational analysis was performed on the Cancer Genome Atlas (TCGA) datasets to explore the role of IL6, IL6R, IL6ST, and IL6R transmembrane isoform expression and their epigenetic regulation in different cancer types." (PMID 34576335, 2021). "Altogether, these studies demonstrate that therapeutic blockade of IL-6R suppresses Bmi-1 function and inhibits cancer stemness." (PMID 34689150, 2021). "The JAK/STAT3 signaling pathway activated by the IL6/IL-6R/IL-6Rβ (gp130) complex plays a key role in the growth and development of many human cancers." (PMID 33363013, 2020).
cancer (continued). "IL6, one of the mediators of the immune/inflammation response and inducers of EMT, can increase cancer-associated stemness and MMP activity and M2 macrophage polarization via the MCT-1/miR-34a/IL-6/IL-6R signaling pathway." (PMID 32268506, 2020). "Although there have been many studies on the relationship between serum IL-6 and clinical outcomes in various cancers, there have been few studies investigating the relationship between IL-6 and IL-6R in tissues and clinical outcomes." (PMID 32138303, 2020). "IL-6R was shown to be important in cancer and RA suggesting that ADAM10-mediated cleavage of IL-6R can be targeted for drug discovery for both indications." (PMID 32435655, 2020). "IL-6 was reported to importantly contribute in cancer growth and progression by activating IL6R-JAK-STAT3 signaling pathway." (PMID 33121520, 2020). "Excessive IL-6 production and dysregulation of the IL6/IL6R axis can lead to inflammation or cancer." (PMID 32957689, 2020). "The fact that the substantial loss of p-STAT3 is seen under conditions affecting only IL-6/IL-6R signaling suggests that the contribution of IL-11/IL-11R to maintaining constitutive p-STAT3 levels in these cancer cells is relatively small." (PMID 31491838, 2019). "Let-7c targets various oncogenes and cancer related genes such as IL6-R (interleukin-6 receptor) or E2F5 (E2F transcription factor 5)." (PMID 31658720, 2019). "The combination of MCT-1 and IL-6/IL-6R pathway cooperatively enhanced cancer stemness and the oncogenic effects." (PMID 30885232, 2019). "IL6, secreted by TAMs, binds to the IL6 receptor (IL6R) on the cancer cell surface to phosphorylate STAT3 (pSTAT3)." (PMID 30927925, 2019). "Then hypoxic cells treated with IL-6R siRNA, Dia, and 5-Aza restored the E-Cad expression making the cancer cells less invasive." (PMID 29695771, 2018). "We evaluated the invasive nature of cancer cells after inhibition of IL-6R or upregulation of MAO-A by using IL-6R siRNA, Dia and 5-Aza." (PMID 29695771, 2018). "Tocilizumab, a humanized anti-IL-6R mAb, is currently the subject of investigation in many clinical cancer trials." (PMID 30671025, 2018). "IL-6R siRNA, Dia, and 5-Aza treatment in hypoxic cells significantly suppressed the number of invasive cancer cells." (PMID 29695771, 2018). "Inhibition of IL-6R and IL-8R using T+R can decrease metastatic burden of cancer cells via the suppression of cell density-dependent migration." (PMID 30220965, 2018). "The proliferating ability of cancer cells was drastically modulated after IL-6R siRNA, Dia, and 5-Aza treatment." (PMID 29695771, 2018). "IL-6 expression in cancer cells seems to be initiated by IL-6 produced by the cells of the IR that through IL-6R leads to the production of IGF-1Ec isoform and to the expression of IL-6 through its canonical pathway." (PMID 30134795, 2018). "The expression and prognostic value of IL6 and the IL6 receptor (IL6R) were explored in The Cancer Genome Atlas (TCGA) and REMBRANDT databases and clinical samples." (PMID 29258522, 2017). "Informed by the TMA results, we assessed the short-term effect of IL-6R inhibition with tocilizumab on the fraction of cancer stem cells in preclinical models of HNSCC." (PMID 29245982, 2017). "The anti-IL6R antibody Tocilizumab, which blocks both membrane-bound and soluble IL6R isoforms, has undergone in vitro testing to evaluate its effects on cancer cell lines." (PMID 29250030, 2017). "Blockade of the IL-6 pathway with a humanized anti-IL-6R antibody (tocilizumab) inhibited endothelial cell-induced motility in vitro and decreased the fraction of cancer stem cells in vivo." (PMID 29245982, 2017). "In the tumor microenvironment, IL-6 activates its receptor (IL-6R) on the cancer cell membrane and promotes the development of cancer in the manner of paracrine and autocrine." (PMID 27174914, 2016).
cancer (continued). "Collectively, the findings presented herein demonstrate that IL-6 in ascites function through membrane-bound IL-6R expressed in cancer cells and increase the EOC cell invasion via JAK2-STAT3 signaling." (PMID 27825119, 2016). "Considering the importance of IL-6 signaling in inflammation and cancer development, several monoclonal antibodies targeting IL-6 or IL-6R have been developed as therapeutic agents for various inflammatory diseases and cancers." (PMID 27080032, 2016). "When CD11b+CD14+ cells were co-cultured with cancer cells, both the invasion and the proliferation of cancer cells were robustly promoted and these promotions were almost completely inhibited by pretreatment with anti-IL-6R antibody (tocilizumab)." (PMID 25658637, 2015). "In all the cases, IL-6R was detected in the cytoplasm and cytomembrane of almost all residual cancer cells, while p-STAT3 was expressed only in the outer layers of the cancer nest." (PMID 25761055, 2015). "Signaling mediated via the interleukin-6 (IL-6)/interleukin-6 receptor (IL-6R) plays a pivotal role during immune responses and in cancer." (PMID 26091352, 2015). "Currently, several monoclonal antibodies (mAbs) and mAb mixtures against IL-6 and IL-6R (in preclinical models) are being developed with encouraging results in cancer cell lines and animal models." (PMID 24670367, 2014). "ADAM family proteases responsible for the shedding of IL-6Rα were also increased on metastasizing cancer-expanded MDSCs." (PMID 24021059, 2013). "The oncogenic effects of AATF may be mediated through its influence on multiple cancer-related signaling pathways, such as the modulation of c-Myc translation, the IL-6/IL-6R signaling axis, and the Src/p190B pathway." (PMID 39911629, 2025). "In contrast, IL-6R expression was relatively low across the dataset, with expression detected in clusters identified as various cell types, including macrophages, myofibroblasts, and cancer cells." (PMID 39858048, 2025). "In cancer prognosis, the expression level of IL6R is considered an important biomarker." (PMID 39893643, 2025). "Interleukin-6 (IL-6) family cytokines activate the JAK/STAT3 pathway via the IL-6Rα/gp130 receptor complex, thereby inducing acute-phase protein synthesis, skeletal muscle proteolysis, and browning of adipose tissue—core phenotypic features of cancer cachexia." (PMID 41002589, 2025). "Consequently, caution should be exercised when employing IL-6R blockade in patients receiving cancer immunotherapy." (PMID 39653766, 2025). "The functional role of IL6R is apparent in cancer, cell differentiation, and inflammation." (PMID 38785970, 2024). "The IL-6 binds to IL-6R on the receptor of cancer cells to induce STAT3 axis." (PMID 39014491, 2024). "Indeed, the IL30/IL6R/gp130 axis promotes inflammatory, immunosuppressive and cancer progression programs and is critical for PC onset and metastasis." (PMID 39232121, 2024). "Also, cGAS-dependent IL-6 secretion and IL6R signaling have recently been demonstrated to provide pro-survival signals in cancer cells, including TNBCs59." (PMID 38167507, 2024). "Our preclinical studies suggested that systematically targeting the MCT-1/IL-6/IL-6R/CXCL7/PD-L1 nexus could be a new medical opportunity that would benefit long-term cancer control and disease-free survival." (PMID 38505617, 2024). "Cancers that have low IL-6R/STAT3 expression and delayed SOCS3 feedback may alternate metabolic activity in a manner similar to MIA PaCa-2." (PMID 38141171, 2024). "The application of IL-6 blockers as anti-cancer agents has been investigated in many cancer types, but the only currently approved monoclonal antibodies (mAbs) in the United States are tocilizumab (anti-IL-6Rα) and siltuximab (anti-IL-6)." (PMID 37047012, 2023).
cancer (continued). "These inflammatory-related proteins play relevant roles in cancer development, such as IL-6R, IL-8 and IL-8RA, which induce tumoral progression, myeloid-derived suppressor cells (MDSCs) chemoattracting, angiogenesis activation, and stem cell property regulation." (PMID 36835258, 2023). "IL1R1 expression predicts poor survival in nearly the same set of cancer types as IL6R." (PMID 37006265, 2023). "The authors suggested that blockade of the IL-6 signaling pathways might reduce production and secretion of IL-6 leading to an increase in the potential effect of the agent involving inhibition of IL-6 or IL-6R in cancer." (PMID 36091805, 2022). "We have verified that both the IL-6 and IL6R may be found on cancer cells from RCC patients with high IL-6." (PMID 32621022, 2021). "The blocking agents that combined with IL-6 and IL-6R may be potential anti-inflammatory drugs, and some of them may be anti-cancer agents." (PMID 33789615, 2021). "Furthermore, we found that cancer cells co-cultured with SCs expressed a higher level of the IL6 receptor (IL6R) and the IL6 signal transducer (gp130), respectively." (PMID 32308766, 2020). "MCT-1 and IL-6/IL-6R pathway can together advance cancer stemness effects." (PMID 30885232, 2019). "Moreover, several studies have highlighted the potential of using inhibitors of IL-6R in preclinical cancer models." (PMID 31491838, 2019). "Similarly, high levels of miR-21 in exosomes of several cancer cell types, including colon cancer, regulate proliferation, migration, and invasion of endothelial progenitor cells by IL6R targeting, and mediate vein thrombosis in patients with cancer." (PMID 31795332, 2019). "Moreover, tocilizumab repressed the MCT-1-induced CD44(+)/CD24(−) subpopulations (55.7%) to the control degree (32.5%), confirming that IL-6R immunotherapy inhibited MCT-1-promoted cancer stemness." (PMID 30885232, 2019). "Therefore, we investigated the expression of IL‐6 receptor (IL‐6R) by immunohistochemistry in KIC and KPC mice and found that IL‐6R was expressed robustly in cancer cells." (PMID 31609088, 2019). "The IL-6R/STAT3/miR-34a loop mediates cancer invasion and metastasis." (PMID 30885232, 2019). "Activation of IL-6/IL-6R and its downstream was found in hypoxic cancer cells." (PMID 29695771, 2018). "Furthermore, knockdown of either IL-6R or STAT3 enhanced the anti-cancer effects of CDDP, as determined by inhibiting the cell viability and reducing the anchorage-independent growth in soft agar." (PMID 27824145, 2016). "High IL‐6 levels and activation of IL‐6:STAT3 signaling has been reported to induce a cancer stem cell phenotype to nonstem cells 28, while IL‐6 trans‐signaling (through IL‐6:IL‐6R) has itself been implicated in 4T1 metastasis." (PMID 26725371, 2016). "Rather, the tocilizumab-mediated decrease in the fraction of cancer stem cells might be attributable to the differential expression of the receptor IL-6R, which is strongly expressed in ALDHhighCD44high cells when compared to ALDHlowCD44low cells." (PMID 26287605, 2015). "IL-6R was detected in the cytoplasm and plasma membrane of almost all the cancer cells and observed in harmony with that of IL-6 in almost all the OSCC cells of the IL-6 high expression group, but not or weakly in the negative and low expression group (data not shown)." (PMID 25761055, 2015). "Exogenous treatment of IL-6 (100 ng/ml, 72h) significantly stimulated VEGF production from cancer cells (control; 239.4 ± 16.3 pg/1x 105 cells, IL-6; 322.4 ± 11.8 pg/1x105 cells) and the pretreatment of cancer cells with anti-IL-6R antibody significantly inhibited VEGF production." (PMID 25658637, 2015). "Our findings identify miR-125b as a potent regulator of Mcl-1 and IL6R, which may provide a novel therapeutic strategy for treatment of HCC and other Mcl-1 or Il6R-driven cancers." (PMID 22942733, 2012).
cancer (continued). "Interestingly, the same treatment reduced he expression of IL-6R in normal cells resulting in a response pattern as found in the corresponding carcinoma cells from the same patient." (PMID 16271139, 2005). "Interestingly, we also found that IL6Rα expression was negatively correlated with pSTAT3 response to IL-10, indicating that heightened IL6Rα and IL-6 in cancer patients may be dominating STAT3 signaling and in turn suppressing the IL-10 responsiveness." (PMID 39389979, 2024). "Curcumin may reverse cancer progression through the inhibition of IL-6R/STAT3." (PMID 39061221, 2024). "Furthermore, we identified several significantly upregulated genes (CD46, JAG1, IL6, and IL6R) that may positively correlate with cancer cells' survival and invasive capabilities in this subtype." (PMID 38571938, 2024). "Anti-IL-6 Ab, such as siltuximab, and anti-IL-6R Ab, such as tocilizumab, have been reported to inhibit both classical signaling and trans-signaling, and their effects have been investigated in various cancer types in preclinical and early-stage clinical studies." (PMID 38469154, 2023). "Interestingly, using either blocking IL-6/IL-6R signaling or PD-1/PDL1 inhibitors may serve as a therapeutic target for sensitizing cancer cells to CAR-T cell treatment and restoring BCA cells to Dox treatment." (PMID 37480115, 2023). "Thus, the role of IL6R expression in cancer can be considered tissue specific." (PMID 37006265, 2023). "Both IL-6 and its receptors (IL-6R and sIL-6R) are, indeed, upregulated in tumors and their increased content in plasma of cancer patients correlates with a poor diagnosis, thus indicating clinical utility of IL-6 as a biomarker or therapeutic target in cancer management." (PMID 31991775, 2020). "Furthermore, IL-6 receptor (IL-6R) expression has been reported in cancer cells." (PMID 32138303, 2020). "Moreover, several known targets of the components of the IL-6R/STAT3/miR-204 loop might be important for cancer progression." (PMID 28388577, 2017). "In order to examine whether STAT3 signaling is also activated in the residual cancer cells after chemoradiotherapy, the expression of IL-6R and p-STAT3 was further examined immunohistochemically in the 12 patients of the high expression group with poor response to chemoradiotherapy." (PMID 25761055, 2015). "Furthermore, the residual cancer cells in the resected specimens expressed IL-6, IL-6R and p-STAT3." (PMID 25761055, 2015). "Finally, miR-34a mimetics may be used to repress s-IL-6R expression and consequently IL-6 trans-signaling, to treat inflammatory diseases and cancer." (PMID 26091352, 2015). "However, the expression of the membrane-bound IL-6R may increase in cancer cells and alternative mechanisms may induce detrimental activation of the IL-6 system." (PMID 24886605, 2014). "This regulation suppresses IL-6/IL-6R/STAT3 signaling activity, leading to reduced proliferation, migration, and invasiveness of cancer cells." (PMID 41179679, 2025). "Previous studies have demonstrated that chemotherapy activates NF-κB via the AKT-IκB pathway and STAT3 via the IL-6R/JAK1 pathway, leading to PD-L1 expression and contributing to chemotherapy resistance in cancer cells." (PMID 40999385, 2025). "Therefore, targeting IL6R may represent a new strategy for treating certain cancers." (PMID 39893643, 2025). "Rather than a SPP1 population expanding only after seeding of metastatic cancer cells, we postulate a mechanism linking primary extrahepatic tumors to premetastatic expansion of an intrahepatic TGF-βR + IL6R + SPP1-KC intermediate macrophage population." (PMID 40335453, 2025). "Chemokines and cytokines, such as IL6/IL6R and CCR2/CCL2, serve as fundamental regulators within the TME, which has been firmly established as a pivotal driving force in cancer progression." (PMID 38468260, 2024).